TIMP2 (TIMP metallopeptidase inhibitor 2)
Diseases named in the same sentence as TIMP2 in open-access papers (continued):
Sharing a sentence is not in itself a finding about the gene and the disease.
psoriasis (4 papers, 2019 to 2025). An autoimmune condition characterized by red, well-delineated plaques with silvery scales that are usually on the extensor surfaces and scalp. "The hypomethylation of p16INK4a, hypermethylation of HLA-C promoter, PDCD5 and tissue inhibitor of metalloproteinases 2 (TIMP2) positively correlate with Psoriasis Area and Severity Index (PASI) scores." (PMID 35722339, 2022). "Fleischmajer and collaborators showed an increase in the expression of MMP2 and TIMP2 in the skin of psoriasis patients, while other researchers showed an increase in the plasma levels of MMP2 and TIMP2 in psoriasis patients compared to the level observed in the plasma of healthy individuals." (PMID 34715781, 2021). "TIMP2 may be a key molecule in the activation of MMP2 in psoriasis and, in this manner, contribute to the inflammatory process." (PMID 34715781, 2021). "The significant increase in the expression of heparanase-1 (HPSE), heparanase-2 (HPSE2), syndecan-1 (SYND1), metalloproteinase-9 (MMP9), and tissue inhibitor of metalloproteinase 2 (TIMP2) in biopsies of skin affected by psoriasis showed extracellular matrix alterations in psoriasis." (PMID 34715781, 2021). "In psoriasis plaques, the levels of MMP9 and TIMP2 were greater than those in skin from healthy controls." (PMID 40756258, 2025). "We found that MMP2, MMP12, MMP13, TIMP2, and TIMP4 distinguished psoriasis from psoriatic arthritis patients undergoing a systemic treatment, with a good diagnostic accuracy (Area under the ROC Curve (AUC) > 0.7)." (PMID 31717649, 2019). "A significant increase in protein and mRNA expression was observed in both heparanases (HPSE and HPSE2), and higher protein levels of MMP9 and TIMP2 were observed in the psoriasis plaque compared to the non-affected skin." (PMID 34715781, 2021). "After the quantitative digital analysis, the protein expression of TIMP2 was found to be higher in the samples of not affected skin from psoriasis patients than in Control tissues 137.16 ± 4.45 ou/μm2 versus 107.16 ± 4.18 ou/μm2 (p < 0.0001)." (PMID 34715781, 2021). "Our results showed an increase in the expression of TIMP2 in psoriasis patients, both in affected and non-affected skin, compared to control samples (blepharoplasty)." (PMID 34715781, 2021). "A set of biomarkers, composed matrix metalloproteinases, and their tissue inhibitors comprises MMP2, MMP12, MMP13, TIMP2, and TIMP4 whose circulating levels are higher psoriasis undergoing systemic therapy compared to the parallel with psoriatic arthritis cohort." (PMID 34715781, 2021). "Moreover, there was a significant increase in HPSE2, SYND1, MMP9, and TIMP2 in non-affected skin samples from patients with psoriasis than in the control sample (tissue obtained by individuals who do not have psoriasis)." (PMID 34715781, 2021). "HPSE2, SYND1, MMP9, and TIMP2 have higher protein expression in the non-affected skin tissue of patients with psoriasis than control tissues, indicating that increased expression of such molecules possibly occurs in the initial stages of the disease even in the absence of psoriatic plaque." (PMID 34715781, 2021).
schizophrenia (4 papers, 2017 to 2024). A major psychotic disorder characterized by abnormalities in the perception or expression of reality. "The concentrations of IL-1Ra, tissue-inhibitor of metalloproteinase-1 (TIMP-1), and TIMP-2 in the schizophrenia group were decreased (all P < 0.001)." (PMID 35223927, 2022). "Genes with consistently lower expression levels in both medial rectus and schizophrenia tissues included NPY1R, TIMP2, and possibly NTRK2." (PMID 29302405, 2017). "Comparing baseline levels between muscle types, three schizophrenia-related genes (NPY1R, NTRK2, TIMP2) had lower levels of expression in medial rectus muscles." (PMID 29302405, 2017). "Lower TIMP-2 has been reported in other psychiatric disorders, including MDD, and schizophrenia." (PMID 37333909, 2023). "The data for inherent, absolute “baselines” of expression between medial and lateral rectus muscles revealed two genes with similar directionalities between EOMs and schizophrenia (NPYR1, NTRK2), while two others (TCF4, TIMP2) went in the opposite direction (slight increase in blood)." (PMID 29302405, 2017). "Three additional schizophrenia-related genes were not examined by PCR-array, but, based on previous microarray studies, are already known to be significantly up-regulated in medial rectus muscles from patients with exotropia: CTGF, TIMP1 and TIMP2." (PMID 29302405, 2017).
thyroid cancer (4 papers, 2007 to 2022). "As predicted, positive MMP-9 and TIMP-2 immunoreactivity was detectable in the cytoplasm of thyroid cancer cells, but rarely in stromal cells or surrounding healthy thyroid tissue." (PMID 24527080, 2014).
acute coronary syndrome (3 papers, 2010 to 2021). Signs and symptoms related to acute ischemia of the myocardium secondary to coronary artery disease. "Moreover, the authors revealed that symptomatic patients with DCE typically present with an acute coronary syndrome and exhibit a lack of obstructive stenosis at angiography, decreased plasma levels of TIMP-2, and raised plasma levels of VEGF." (PMID 34572455, 2021).
acute lymphoblastic leukemia (3 papers, 2015 to 2025). Leukemia with an acute onset, characterized by the presence of lymphoblasts in the bone marrow and the peripheral blood. "TIMP2 was positively correlated with apoptosis (R = 0.501, P = 0.001) and negatively correlated with angiogenesis (R = −0.388, P = 0.015) in acute lymphoblastic leukemia." (PMID 36304987, 2022).
adenoma (3 papers, 2011 to 2025). A neoplasm arising from the epithelium. "Conversely, TIMP2 showed a significant increase in adenomas (mean: 3.63) compared to adenocarcinomas (mean 3.07, p = 0.0001)." (PMID 40699620, 2025). "Paired analysis confirmed this trend, with 73% of paired samples showing a decrease in TIMP2 expression in adenocarcinomas relative to their matched adenomas." (PMID 40699620, 2025). "The immunoreactivity for MMP-13 and TIMP-2 was lower in carcinomas than in adenomas, confirming the mRNA data for MMP-13 and the other MMP inhibitors that were evaluated." (PMID 21726449, 2011). "The percentage of TIMP-2- and MMP-13-positive fibroblasts was higher in adenomas than in carcinomas." (PMID 21726449, 2011). "Immunohistochemical staining revealed that TIMP-2 and MMP-13 were more highly expressed in simple adenomas than in simple carcinomas." (PMID 21726449, 2011).
astrocytomas (3 papers, 2015 to 2024). "Similar results were obtained in astrocytomas: specifically, in the genes MMP3, MMP8, MMP10, TIMP2, and TIMP4." (PMID 38474106, 2024). "Among these, Sulfhydryl oxidase 1 (Qsox1), involved in tumor cell invasion and subsequent metastasis was found downregulated in cluster 1 such as CD166, TIMP2 and AGT knew to be involved in astrocytoma (cluster 1)." (PMID 33402730, 2022). "We examined the mRNA expression profiles of RECK transcripts, as well as of MMPs reportedly inhibited by canonical RECK (MMP-2, -9 and -14), and of endogenous tissue inhibitors of MMPs (TIMP-1, TIMP-2, TIMP-3 and TIMP-4) in astrocytomas of different grades of malignancy." (PMID 26431549, 2015). "TIMP-2 is not differentially expressed among the different grade astrocytomas." (PMID 26431549, 2015).
brain injury (3 papers, 2011 to 2023). Acute and chronic (see also brain INJURIES, CHRONIC) injuries to the brain, including the cerebral hemispheres, CEREBELLUM, and brain STEM. "Together, these findings suggest that Col1α1+ fibroblasts repair BBB damage and hemorrhagic brain injury partially via TIMP2." (PMID 36417884, 2022). "Interestingly, TIMP-2 expression has also been described in microglia following brain trauma." (PMID 21631912, 2011).
brain tumor (3 papers, 2015 to 2024). "The protein expression of MMP9, MMP13, TIMP1, TIMP2, and TIMP4 was elevated in all three investigated brain tumor diagnoses." (PMID 38474106, 2024).
cardiomyopathy (3 papers, 2014 to 2021). A disease of the heart muscle or myocardium proper. "Levels of TIMP-1 and TIMP-2 were also higher in Tc+ stage CD compared to Tc+ stages A and B. Like other cardiomyopathies, Chagas heart disease involves substantial tissue remodeling and progressive fibrosis; the changes seen in MMP and TIMP levels are a reflection of the severity of these processes." (PMID 25275382, 2014). "TIMP2 mRNA expression was significantly downregulated but mRNA levels of MMPs were not different in pigs with anthracycline-induced cardiomyopathy compared to controls." (PMID 34052857, 2021). "BNP, NTproBNP, troponin I, MMP-2, TIMP-1, and TIMP-2 levels rose with increasing severity stage but did not distinguish between Chagas cardiomyopathy and other cardiomyopathies." (PMID 25275382, 2014). "We showed significant elevations in BNP, NTproBNP, Troponin I, MMP-2, TIMP-1 and TIMP-2 among Tc+ individuals with cardiomyopathy compared to those without heart disease, findings consistent with previous studies." (PMID 25275382, 2014).
carotid atherosclerosis (3 papers, 2024 to 2025). A thickening and loss of elasticity of the walls of carotid arteries that occur with formation of atherosclerotic plaques. "Indeed, we reported the association of the MMP-2/TIMP-2 system with carotid atherosclerosis and cardiovascular risk in patients with severe CKD on dialysotherapy." (PMID 38610612, 2024). "Our previous studies demonstrated increased circulating MMP-2 and TIMP-2 levels in patients with CKD, which was associated with hypercoagulability, oxidative stress, inflammation, carotid atherosclerosis, and cardiovascular risk." (PMID 38610612, 2024).
cholesteatoma (3 papers, 2021 to 2024). A pathologic process characterized by the proliferation of keratinizing squamous epithelium resulting in the accumulation of keratin and cells in the middle ear and/or mastoid. "The decreased number of TIMP-2 and increased MMP-2 in patient groups compared with the control group are the cause of the intensive remodulation in patients with cholesteatomas." (PMID 38535082, 2024). "We substantiate this by the increased amount of MMP-2 and decreased TIMP-2 in the cholesteatoma groups compared with control skin, as well as positive correlations between MMPs and TIMPs in the cholesteatoma tissue." (PMID 38535082, 2024). "In our study, we found a positive correlation between NF-κβ and TIMP-2 in adult and pediatric cholesteatoma." (PMID 38535082, 2024). "Nevertheless, the difference between the TIMP-2 in the matrix and that in the skin epithelium was nearly statistically discernible (p = 0.055) and was decreased in the cholesteatoma tissue, in contrast to the skin." (PMID 36837507, 2023). "Intercorrelations between VEGF, NF-κβ and TIMP-2 induce neo-angiogenesis in adult cholesteatoma." (PMID 36837507, 2023). "Therefore, we suggest that TIMP-2 intercorrelates with VEGF in cholesteatoma tissue and that reduced relative numbers of TIMP-2 mean reduced anti-angiogenetic properties in cholesteatoma tissue, which results in increased neo-angiogenesis." (PMID 36837507, 2023). "Yet, it is still unclear how exactly TIMP-2 affects MMP-2 or MMP-9 in cholesteatoma tissue." (PMID 34682191, 2021). "Additionally, TIMP-4 was significantly more expressed in cholesteatoma tissue than TIMP-2." (PMID 38535082, 2024). "Intercorrelations between TIMP-2, NF-κβ and VEGF induce neo-angiogenesis in adult cholesteatoma." (PMID 36837507, 2023). "TIMP-2 presented variance in the cholesteatoma matrix and perimatrix, ranging from a lack of positive cells to numerous (+++) immunoreactive cells." (PMID 34682191, 2021). "To explain this correlation, we searched the literature and found that TIMP-2 can directly regulate NF-κβ and prevent cells from apoptosis; thus, we could speculate that TIMP-2 may also affect NF-κβ and induce cell proliferation in cholesteatoma tissue." (PMID 38535082, 2024).
chondrosarcoma (3 papers, 2013 to 2020). A malignant cartilaginous matrix-producing mesenchymal neoplasm arising from the bone and soft tissue. "At the protein level, TIMP2 expression correlates with that of MMP2 and MMP14 in chondrosarcoma, all three proteins displaying elevated levels in high-grade anaplastic components compared to low-grade components of de-differentiated and conventional chondrosarcoma." (PMID 31466240, 2019). "However, this mode of binding appears to be insufficient to support bridging to LRP-1 in a complex biological environment, as we found that neither TIMP-1 nor TIMP-2 could increase the rate of MMP-1 endocytosis by HTB94 chondrosarcoma cells." (PMID 32694578, 2020).
chronic rhinosinusitis (3 papers, 2020 to 2021). Chronic form of sinusitis. "Pathogenesis of chronic rhinosinusitis might also be related to the regulation of MMP-2 and TIMP-2 expressions." (PMID 33777140, 2021). "CSE may contribute to the pathogenesis of chronic rhinosinusitis by regulating MMP-2 and TIMP-2 expression." (PMID 32806646, 2020).
cognitive decline (3 papers, 2023 to 2024). "A potential limitation of our study is its cross-sectional design, which constrains the investigation of the association of TIMP2 protPRSs with longitudinal cognitive decline rates." (PMID 39483923, 2024). "Future research should consider longitudinal study designs to explore the relationship between TIMP2 protPRSs and cognitive decline rates over extended follow-up periods." (PMID 39483923, 2024). "Together with the comprehensive assessment of the MMP inhibitory and binding impacts of these engineered proteins, these data provide important details for a therapeutic path forward for TIMP2 recombinant proteins in aging-related cognitive decline." (PMID 37321845, 2023). "In the memory clinic cohort, baseline MMP and TIMP levels did not predict faster functional and cognitive decline over time, although TIMP-2 levels were found to be increased in MCI patients who converted to dementia." (PMID 37221606, 2023).
dementia (3 papers, 2023 to 2025). Loss of intellectual abilities interfering with an individual's social and occupational functions. "Compared to the CU stage, the dementia stage was associated with increased TIMP-2 levels for both sexes, but a significant effect of MCI was only evident in women (β = 0.32, P < 0.01)." (PMID 37221606, 2023). "For example, elevated levels of MMP-2, MMP-3, MMP-10, TIMP-1, and TIMP-2 were detected in the CSF of patients with delirium who had pre-existing dementia." (PMID 40507855, 2025).
dysplasia (3 papers, 2014 to 2025). A usually neoplastic transformation of the cell, associated with altered architectural tissue patterns. "At the cutaneous level, TIMP-2 expression correlates with the degree of dysplasia and is higher in lesions with severe dysplasia compared to those associated with mild dysplasia or in perilesional skin." (PMID 40724562, 2025). "The expression of MMP-2 and TIMP-2 in the basal and parabasal cells of the overlying epithelium as well as in the fibroblasts of the lamina propria in most of the cases of dysplasia has been shown by other investigators." (PMID 24591757, 2014). "The disparity in TIMP-2 and MMP-2 expression among healthy oral tissue and dysplasia was significantly different, indicating that TIMP-2 may be significant in advancing premalignant lesions." (PMID 40283497, 2025). "A retrospective immunohistochemical study was carried out on 30 clinically and histologically proven cases of leukoplakia with dysplasia and 10 cases of normal buccal mucosa using anti-MMP-2 and anti-TIMP-2 monoclonal antibodies." (PMID 24591757, 2014).
esophageal squamous cell carcinoma (3 papers, 2015 to 2023). Esophageal squamous cell carcinoma (ESCC) is a type of esophageal carcinoma (EC) that can affect any part of the esophagus, but is usually located in the upper or middle third. "For example, it has been demonstrated that miR-4443 promotes the metastatic properties of breast cancer and esophageal squamous cell carcinoma by suppressing the tissue inhibitors of metalloproteinase 2 (TIMP2)." (PMID 38008717, 2023).
exfoliative glaucoma (3 papers, 2008 to 2025). "In pseudoexfoliative glaucoma (PEXG), the enzyme balance between MMP-2 and TIMP-2, already impaired by the pseudoexfoliative syndrome (PEX), is seriously altered even compared with POAG." (PMID 18939999, 2008). "The aim of this study was to assess changes in metalloproteinases (MMP-2) and tissue inhibitor of metalloproteinases (TIMP-2) following selective laser trabeculoplasty (SLT) in patients with pseudoexfoliative glaucoma (PEXG)." (PMID 18939999, 2008). "Furthermore, in patients with exfoliative glaucoma, the reduction in IOP after SLT correlated with a decrease in the ratio between TIMP2 and MMP2." (PMID 39769228, 2024).
glomerulosclerosis (3 papers, 2022 to 2024). A hardening of the kidney glomerulus caused by scarring of the blood vessels. "In addition, both TIMP1 and TIMP2 are associated with glomerulosclerosis." (PMID 35045102, 2022).
Hernia (3 papers, 2021 to 2025). "Similar up-regulation of active MMP-2 with relative reduction in TIMP-2 is detectable in abdominal skin fibroblasts from hernia patients, consistent with a broader connective-tissue susceptibility beyond the hernia margin." (PMID 41440470, 2025). "Conversely, direct hernia fascia shows decreased TIMP-2 immunostaining compared to controls and indirect hernia, a shift that would favor sustained MMP-2 activation and collagen loss." (PMID 41440470, 2025). "Additional work on tissue inhibitors of metalloproteinases (TIMPs) revealed decreased TIMP-2 expression in fascia transversalis of hernia patients, further shifting the balance toward excessive collagen breakdown." (PMID 41440470, 2025). "On the other hand, TIMP-2 exhibited high expression levels in the control group, while significantly lower expression levels were recorded in the hernia group." (PMID 37509159, 2023). "Additionally, TIMP-2 exhibited maximal expression in the control group while the hernia group displayed significantly decreased expression levels." (PMID 37509159, 2023).
hydronephrosis (3 papers, 2020 to 2022). Collection of urine in the renal pelvis that results in dilatation of the renal pelvis and calyces. "This study evaluates serum and urinary metalloproteinases MMP-1, MMP-2, and MMP-9 and tissue inhibitors of metalloproteinases TIMP-1 and TIMP-2 as potential biomarkers of ON in children with congenital unilateral hydronephrosis (HN) caused by UPJO." (PMID 32670438, 2020). "Urinary MMP-2, MMP-7, TIMP-2, and NGAL were measured as well as clinical characteristics including hydronephrosis grade, differential renal function, t1/2, and UPJO etiology." (PMID 35834547, 2022).
idiopathic pulmonary fibrosis (3 papers, 2013 to 2022). Idiopathic pulmonary fibrosis (IPF) is a nonneoplastic pulmonary disease that is characterized by the formation of scar tissue within the lungs in the absence of any known cause. "Bleomycin-induced idiopathic pulmonary fibrosis (IPF), a disease characterized by chronic, progressive scarring of the lungs associated with a decline in respiratory function, induces the expression of both TIMP1 and TIMP2 in the alveolar and interstitial compartments." (PMID 36624735, 2022).
Inguinal hernia (3 papers, 2021 to 2023). Protrusion of the contents of the abdominal cavity through the inguinal canal. "In contrast, previous studies have reported a decrease in TIMP-1 levels and an increase in TIMP-2 levels specifically in the serum of patients with inguinal hernias." (PMID 37509159, 2023). "The roles of TIMP-1 and TIMP-2 in the context of inguinal hernias (IHs) have been extensively studied." (PMID 37509159, 2023).
intracranial hemorrhage (3 papers, 2013 to 2015). Bleeding within the SKULL, including hemorrhages in the brain and the three membranes of MENINGES. "However, introduction of homozygous Timp2 mutation greatly reduces the extents of brain hemorrhage in comparison to that in orc3 single mutants." (PMID 23349620, 2013).